CD44 (CD44 molecule (IN blood group))
Diseases named in the same sentence as CD44 in open-access papers (continued):
Sharing a sentence is not in itself a finding about the gene and the disease.
tumor (continued). "The cell surface markers CD133 and CD44 are critical for identifying TNBCSCs and maintaining their tumor-initiating capacity, facilitating self-renewal and metastasis." (PMID 40730501, 2025). "CD44 is widely recognized as a key marker of cancer stem cells (CSCs) and contributes to tumor progression, metastasis, and resistance to therapy." (PMID 40259468, 2025). "Wang’s research employed magnetic carbon nanotubes conjugated with CD44 antibody for neoplasia therapy, demonstrating significant tumor reduction via endocytosis-mediated uptake and mitochondrial apoptosis in GBM cell lines G361 and G440." (PMID 40771723, 2025). "Re-expression of miR-708 led to the downregulation of several oncogenic targets including Rap1B, IKKβ, and CD44, all of which contribute to tumor proliferation, invasion, and stemness." (PMID 41008798, 2025). "Several studies have highlighted the crucial role of C1GALT1‐mediated O‐glycosylation in regulating the surface localization and stability of transmembrane glycoproteins such as MUC1, CD44, and IL‐6 receptor, thereby impacting tumor growth and metastasis." (PMID 39844613, 2025). "The percentage of CD44-positive cells varied significantly depending on the degree of tumor differentiation." (PMID 40005368, 2025). "High expression of CD44 variants has been associated with stem-like properties and chemoresistance in ATC, both of which are linked to the tumor’s aggressive behavior and poor prognosis." (PMID 40363706, 2025). "Individual differences of the stem cell associated markers CD24 and CD44, as well as MHC- and PD-L1 expression on tumor cells of HNSCC patients were detectable using flow cytometry." (PMID 40860824, 2025). "According to the results of cell–cell communication analysis among C2, C5, and other clusters, terminal states of tumor-infiltrating CD4+ T cells were specifically enriched in the MIF signal pathway (MIF-CD74+CD44, MIF-CD74+CXCR4)." (PMID 41008548, 2025). "From the 29 selected TNBC patients, tumor samples from 22 were available for biomarker analysis including BCSC markers (CD44, CD24, ALDH1) and immunogenic markers (PD-L1, and TILs)." (PMID 40362201, 2025). "HNSCC CSCs can be identified by the isolation of sphere-forming cells (tumour spheres) as a marker of self-renewal, and the expression of stem cell markers such as CD44 and ALDH1." (PMID 40282522, 2025). "CD44 facilitates the tumor cells’ interaction with the extracellular matrix, enhancing the physical barrier around tumor cells and contributing to an immunosuppressive microenvironment." (PMID 40075578, 2025). "Accumulation of hyaluronan together with increased synthesis of CD44 and specific HYALs correlate with tumor progression and reduced overall patient survival in certain types of tumors." (PMID 40542654, 2025). "In MGs, CD44 is known to regulate essential biochemical processes such as tumour cell adhesion, angiogenesis, proliferation and inflammation." (PMID 39316249, 2025). "The P-value was 0.02, indicating a statistically significant correlation between CD44 expression and the histological grade of the tumor." (PMID 40881916, 2025). "On day 4 after RT, we observed a distinct upregulation of CD25, CD44 and the proliferation marker Ki67 on tumor-infiltrating CD8+ T cells preferentially in mice receiving 1 × 20 Gy, which contrasted with 3 × 8 Gy-treated and non-treated animals." (PMID 40502703, 2025). "The study found that the MIF-(CD74+CD44) complex play a significant role in tumor development by promoting immune cell migration and activation." (PMID 40110199, 2025). "CD44+ tumor cells then triggered the phenotypic transition of CAFs into iCAF-like and myCAF-like cells through PTN signaling." (PMID 40069574, 2025). "The strong affinity between hyaluronic acid (HA) and the CD44 protein facilitated the selective uptake of SnO2−x@SiO2-HA nanoparticles by CD44-overexpressing tumor cells, enabling precise targeting and treatment." (PMID 41012514, 2025).
tumor (continued). "The complex, CD44-rich tumor microenvironment of these tumors, adapted to evade standard antibody treatments, poses significant obstacles." (PMID 40075578, 2025). "In contrast, CDH18 showed negative correlations with TNFSF14, TNFSF15, PDCD1, TNFRSF14, and CD44, genes reported to play critical roles in tumor inhibition." (PMID 40017628, 2025). "Evidence suggests that CD44-mediated cellular processes including inflammation, wound healing, tumour formation, and cell migration also require RHAMM surface expression." (PMID 41301516, 2025). "Tumor-infiltrating E7/H2Db tetramer+CD44+CD8+ T cells were plotted against tumor weight 22 days after TC-1 inoculation, revealing a significant negative correlation (R2 = 0.565, P = 0.0194) between them only for the E743–77-pulsed bm12 mBMDC vaccination group." (PMID 40857404, 2025). "SPP1 derived from tumor and immune cells activates CAFs via the CD44 signaling pathways, enhancing the secretion of collagen (COL1A1, COL1A2) and fibronectin (FN1)." (PMID 41391064, 2025). "COX-2 and its downstream product, PGE2, are crucial in creating an inflammatory microenvironment in tumor tissues and maintaining stemness, as indicated by the presence of stem cell markers, including CD44 and SOX9." (PMID 40244228, 2025). "In this study, the majority of cases, i.e., 28 (46.6%), had tumor sizes between 2 and 5 cm (T2) and showed CD44 positivity, with a statistically significant correlation (P < 0.05)." (PMID 40881916, 2025). "Several strategies, including CD44-targeting monoclonal antibodies and inhibitory peptides, are in various phases of preclinical and clinical development to deal with chemoresistance, tumor regrowth and metastases of CD44-overexpressing malignancies." (PMID 40342488, 2025). "Cell communication analysis suggested that SPP1 secretion by tumor cells binds to CD44 on neoplastic stem cells, activating the PI3K/AKT pathway and enhancing lncRNA transcription." (PMID 40076844, 2025). "Meanwhile, ZEB1 blockade attenuates CD44+ neutrophil–induced CD8+ T cell exhaustion by reducing tumor-derived SPP1 secretion, which otherwise promotes exhaustion through activation of the PD-L1/PD-1 pathway." (PMID 40924501, 2025). "In cancer, CD44 is highly upregulated in CSCs, where it is considered a critical molecular marker for tumor initiation and progression, particularly in breast, gastric, and prostate cancers." (PMID 41391064, 2025). "The role of CD44 as a CSC marker in HNSCC has been the subject of extensive research, showing associations with tumor growth, metastasis and chemo-radiotherapy resistance." (PMID 40738059, 2025). "We found that 9D9 increased the absolute numbers of tumor-infiltrating CD44+PD-1+ CD8+ T cells, stem-like/progenitor exhausted (SLAMF6+TIM3−) and effector/terminally exhausted (SLAMF6−TIM3+) CD8+ T cells." (PMID 40460830, 2025). "CAR-T cells with a central memory cell phenotype characterized by expression of CD62L and CD44 (CD62L+ CD44hi) exhibit high anti-tumor activity." (PMID 39925817, 2025). "Tumor cells can promote M2 macrophage polarization in the TME through the CHI3L1/CD44/PI3K/AKT axis." (PMID 41174767, 2025). "Different CD44 isoforms exhibit distinct functions in interacting with ligands and other binding molecules, emphasizing their role in diverse tumor progression in humans." (PMID 41049281, 2025). "Laboratory tests remarkably found that the knockdown of CD44 reduces tumor cell adhesion to endothelial cells in vitro, and decreases overall tumor burden in the brain, lung, liver and skeleton as well as increased cell survival in vivo experiments." (PMID 39430073, 2024). "Implanting ALDH+/CD44+ CSCs in mice led to tumor formation due to signaling with endothelial cells and formed greater colonies." (PMID 38737455, 2024). "CD44 glycoproteins are potentially important markers of tumor progression that participate in the metastatic cascade." (PMID 38790166, 2024).
tumor (continued). "We measured a dose dependent increase in CD-44 relative expression in tumour cells cultured in a stiffer microenvironment." (PMID 38172135, 2024). "In this context, the phenotype of Ter-cells is CD45-Ter119+ CD71+CD41+CD44+, and they mainly exist in the spleen of advanced-tumor bearing hosts; however, a few can also be found in the tumor." (PMID 39474425, 2024). "We investigated the expression of SOX4 and CD44 in our tumor samples from xenograft mice treated with IBRD9 and in untreated tumors." (PMID 37739089, 2024). "CD44, the tumor growth and metastasis-promoting factor, binds various extracellular matrix components, primarily hyaluronic acid (HA)." (PMID 38903499, 2024). "Clorgyline, a MAOA inhibitor, effectively suppresses tumor development in mice, increasing caspase three levels and decreasing IL-6, pSTAT3, STAT3, and CD44 production in tumor cells." (PMID 39092186, 2024). "We also identified a conserved interaction between tyrosinase binding protein (TYROBP) present on hybrid cells and CD44 present on tumor cells, in all patients." (PMID 39030653, 2024). "A shikonin-loaded system targeting CD44 demonstrates the potential to inhibit tumor growth and liver metastasis by reprogramming immunometabolism through PKM2 inhibition." (PMID 39010066, 2024). "Here the authors show that iRhom1 regulates sensitivity to chemotherapy and immune response, as well they report that CD44 targeting nanoparticle-mediated co-delivery of iRhom1 pre-siRNA promotes anti-tumor immune responses in preclinical cancer models." (PMID 38177179, 2024). "In fibroblasts to epithelial cells interactions, various LAMININ molecules play a key role in different stages of tumor development, and the Laminin-CD44 interactions in fibroblasts to T cells exhibited a clear downward trend with tumor development." (PMID 38278958, 2024). "In PC3 cell tumor spheroids treated with LP-Quer-HA, a decrease in the number of CD44 cells and a reduction in the expression of CD44, Oct3/4, and Wnt were observed." (PMID 39416904, 2024). "CD44 is a cell membrane protein that plays an important role in tumor microenvironments (TMEs), specifically between cell-to-cell interactions and cell-extracellular matrix (ECM) connections." (PMID 39547513, 2024). "In the field of tumor therapy, hyaluronic acid (HA) can be applied in combination with CD44 for drug targeting." (PMID 39339402, 2024). "These CNs were defined based on their overall cellular composition and classified as Vasculature, Immune Warm and Cold Parenchyma, Bulk Tumor, MDSCs, PD-L1/PD-1, HLA-A, CD44 Immune, Proliferating, Inflammation, SMAs, and Undefined CNs." (PMID 39333065, 2024). "The activation marker CD44 was highly expressed in tumor-infiltrating CD8+ and CD4+ T cells, but CD8+ T cells in KO tumors expressed significantly lower levels of CD44 than did those in WT tumors." (PMID 38618956, 2024). "The TEID is composed of galactose and neuraminidase conjugated streptolysin O (SLO‐Gal and SLO‐NEU), which are encapsulated in a hyaluronic acid (HA) shell for targeted recognition to tumor tissue via cell surface CD44." (PMID 37870206, 2024). "Using a pan‐CD44 kd approach, we obtained direct in vivo evidence that CD44 promotes tumor growth and spontaneous distant metastasis to multiple sites in the HT‐29 xenograft model." (PMID 37849446, 2024). "CD44 is widely studied in the context of various types of cancer due to its role in cell adhesion and migration and its use as a tumor stem cell marker." (PMID 39684268, 2024). "Integrin beta-1 (ITGB1, CD29) and CD44, with their widespread expression in various cell types, are both key mediators of tumor invasion, metastasis, and resistance in GBM and other cancers." (PMID 39594703, 2024). "Combined with TCGA and CGGA cohort, TRIM56 was most closely correlated with LAIR1, CD44, PDCD1LG2 and CD274, and oncoplots were used to display the tumor mutation gene microlandscape of TRIM56 high expression group and low expression group." (PMID 38348047, 2024).
tumor (continued). "Studies have shown that the serum levels of CD133 and CD44, reflecting CSC activity, are significantly associated with tumor metastasis, recurrence, and prognosis." (PMID 38675202, 2024). "Currently, the role of CD44 in tumor-related clinical outcomes is still contradictory, and therefore further investigations are required to fully clarify the specific role of different CD44v in patient prognosis." (PMID 38600583, 2024). "Nanoparticles composed of CS, doxorubicin, and bovine serum albumin targeting CD44 were reported to suppress 4T1 tumor growth." (PMID 38783892, 2024). "Tumor-associated dendritic cells (TADCs) secreted CXCL1, which in turn increased the expression of the CSC markers CD44 and CD133 on the SW620 CRC cell line and promoted their stemness." (PMID 38254219, 2024). "Despite the promising therapeutic potential of CD44 as a tumor target, the side effects of targeting CD44, such as severe skin toxicity, are the greatest obstacles to clinical treatment due to the wide and high-level expression of CD44 in normal tissues." (PMID 39145451, 2024). "HMW-HA binding with CD44 mediates CD44 clustering, resulting in the activation of the tumor-suppressive Hippo pathway." (PMID 39680591, 2024). "The results from the present study, in particular, show that CD44 expression was increased in the st-FL tumor along with several members of the CD11a/b family (ITGA1, ITGA5, ITGB1, ITGAV), and all integrins were involved in cellular adhesion and migration." (PMID 39456647, 2024). "After 28 days of tumor cell transplantation, CD44+A549 cell tumorigenicity was significantly improved." (PMID 39457544, 2024). "Using a CD44v6‐specific antibody, which specifically labels the products of CD44 isoforms 1 and 2, we observed immunoreaction of the murine tumor stroma only, which was also visible in the kd tumors and in lung metastases (lower row)." (PMID 37849446, 2024). "The roles of CD44 have been widely explored in a variety of cancers for tumor progression, metastasis, chemoresistance, and angiogenesis." (PMID 39518076, 2024). "It is therefore possible that the promotion of tumor cell adhesion of mesothelial cells by IL‐17A+TNF is partly mediated by an enhanced interaction of CD44 with hyaluronan." (PMID 38566518, 2024). "A recent study investigated expression of CD44 and potential relationships with elements of 33 different cancer types that make them more susceptible to ICI treatments, including tumor mutational burden (TMB) and microsatellite instability." (PMID 38539529, 2024). "Several genes associated with tumour cell proliferation and survival (CCND1, AKT1 and CD44) were more highly expressed in p16-/HPV- tumours relative to p16+/HPV+." (PMID 39328208, 2024). "Tumor biopsy samples are used to detect common markers, including CD44, CD24, and ALDH1, by the immunohistochemistry (IHC) method." (PMID 39001543, 2024). "CD44, as a cell surface glycoprotein, has been reported in multiple tumor types as a marker for stem-like tumor cell populations." (PMID 39518076, 2024). "Interaction of OPN with CD44 activates multiple signaling pathways, which in turn promote tumor growth." (PMID 39062100, 2024). "In mouse models of melanoma (B78ChOVA and B16ChOVA) and spontaneous breast cancer (MMTV-PyMTChOVA), rapid exhaustion of TAMs resulted in decreased expression of exhaustion markers PD-1, CD38 and TOX on tumor-infiltrating CD44+OT-ICD8+T cells." (PMID 38279145, 2024). "Blocking the interaction of OPN with αvβ3 integrin resulted in decreased expression of MMP-2, ILK and uPA, whereas blocking CD44 interaction resulted in decreased tumor growth in mouse mammary epithelial cancer cells." (PMID 39062100, 2024). "CD44 is frequently upregulated in hematological and epithelial malignancies, promoting tumor survival and metastasis, but off-tumor expression (including on HSCs) precludes TCRT development." (PMID 39095991, 2024).
tumor (continued). "The decrease in human CD44 expression in the mice tumor tissues in the low dose of doxorubicin and compound 1e or PD153035‐treated group was comparable to that of the high dose of the doxorubicin‐treated group." (PMID 38522013, 2024). "Double immunohistochemical staining showed a reduction in the number of CD44+/ALDH + cells in shNSDHL tumor tissues." (PMID 39516821, 2024). "In HNSCC, targeting CD44 was found to decrease tumor growth and CSCs by inhibiting PI3K–4EBP1–SOX2 signaling." (PMID 38783892, 2024). "In biopsy specimens of smoking patients, we found a significant association of CD44, KRT4, and KRT13 expression with IL6 gene expression, the level of which was increased in tumor tissue of smokers compared to peritumor tissue." (PMID 38540309, 2024). "In this study, we confirmed the key role of CD44 in promoting tumor proliferation, migration, and invasion of colorectal tumor cells in vitro." (PMID 38590654, 2024). "Numerous studies have shown that cancer cells with the CD44+ surface marker possess characteristics of tumor stem cells, such as self-renewal and tumor initiation." (PMID 38714724, 2024). "An increased risk for treatment resistance and metastasis is highly prevalent in patients with high tumour expression of CD44." (PMID 38816670, 2024). "Our analyses of clinical tumor samples suggest that CD44 isoforms 3 and 4 play opposing roles in CRC metastasis." (PMID 37849446, 2024). "CD44 expression was significantly associated with PD-L1 expression (p = 0.030, OR: 9.429, 95% CI: 1.058–84.037) and marginally associated with PNET tumor type (p = 0.053, OR: 4.242, 95% CI: 0.935–19.256)." (PMID 39148690, 2024). "These neutrophils were found near αSMA-expressing myofibroblasts, PanCK-positive tumor cells, CD44-expressing tumor stem cells, and dendritic and macrophage populations, suggesting a complex, immune-rich TME." (PMID 39351436, 2024). "The clinical relevance of our experimental findings was supported by immunohistochemical staining analyses demonstrating that the expression of HDAC7, ITGB1, LGALS3 and CD44 was highest in GBM tumours and was negatively correlated with SOX8 expression." (PMID 39629136, 2024). "CD44 is a common coreceptor that participates in several signaling pathways and is involved in tumor progression." (PMID 38243273, 2024). "We found that CD44+TCF-1–CD8+ T cells in the tumor after combined RT and CD86 blockade expressed PD-1, albeit to a lesser extent than did CD44+TCF-1+CD8+ T cells." (PMID 38349740, 2024). "Glabridin inhibits the TGF-β/SMAD2 pathway by upregulating miR-148a, reducing cancer stem cell markers (CD44, EpCAM), and impairing self-renewal, tumor sphere formation, and independent growth." (PMID 39723390, 2024). "MMPs, including MT1-MMP, MMP2, and MMP9, are also involved in the CD44-promoted formation of new vasculature and tumour invasion, which can be enhanced by an activation of TGF-β with proteolytically activated MMP-9." (PMID 38791985, 2024). "This phenomenon is attributed to the re-expression of CD44 in lymph nodes, which guides the homing of tumor cells to lymph nodes." (PMID 39619442, 2024). "For instance, the interaction between the glycoprotein SPP1 and the cell surface receptor CD44 has been found to inhibit T cell activation and proliferation, as well as promote tumor immune evasion." (PMID 38515213, 2024). "In the contest of CD44-targeted antibodies, monoclonal antibody (mAb)-modified Doxil against CD44 showed a significant improvement in cellular uptake and higher doxorubicin concentration inside tumor cells than Doxil in CD44-expressing murine CRC cells." (PMID 38672650, 2024). "CD44 is a hyaladherin, and HA-CD44 interaction has been shown to promote tumor cell survival and chemoresistance." (PMID 38724670, 2024). "It is worth noting that IDO1, IDO2, CD44, and CD200 are up-regulated in the FRM high-risk group, all of which are related to the tumor microenvironment." (PMID 38534739, 2024).